EGFR (epidermal growth factor receptor)
Diseases named in the same sentence as EGFR in open-access papers (continued):
Sharing a sentence is not in itself a finding about the gene and the disease.
lung cancer (continued). "Therefore, targeting EGFR is considered an efficient therapeutic strategy against lung cancer, particularly for inhibiting EGFR phosphorylation by using gefitinib and afatinib." (PMID 28787001, 2017). "Down-regulation of SCD1 obviously compromised EGFR-promoted lung cancer cell growth." (PMID 28724430, 2017). "This mutation has been described twice in lung cancer (COSMIC databank accessed 31.10.2016) with no data on response to EGFR-TKI therapy given in the literature." (PMID 29100434, 2017). "Furthermore, a plenty of miRNAs have been shown to reduce sensitivity and acquired resistance to EGFR-TKI in lung cancer cells, including miR-23a." (PMID 28415568, 2017). "EGFR overexpression exceeds 90% in lung cancer, acting as a target for potent therapeutic agents." (PMID 28787001, 2017). "For example, EGFR is a target for molecularly targeted agents in lung cancer therapy." (PMID 28125617, 2017). "Recently, increasing numbers of miRNAs have been correlated with the drug resistance of lung cancer cells to anti-EGFR agents, indicating that miRNAs may serve as novel targets or promising predictive biomarkers for anti-EGFR therapy." (PMID 28430586, 2017). "In addition, Tid1 was also reported to inhibit EGFR signaling in lung cancer cells by promoting ubiquitinylation and degradation of EGFR." (PMID 28914774, 2017). "In lung cancer, dysregulation of EGFR signaling is frequently found." (PMID 28430586, 2017). "Unlike EGFR mutation in lung cancer, which is more prevalent in Asians than in Caucasians, the frequency of FGFR1 amplification in ESCC does not seem to be widely different by ethnicity." (PMID 29179482, 2017). "Their mathematical modeling proposed that alternative therapeutic strategies could prolong the benefit of TKI against EGFR-mutant lung cancer by delaying the development of resistance." (PMID 28615068, 2017). "In conclusion, statins might potentially enhance the therapeutic effect and increase survival in patients with lung cancer receiving EGFR-TKI therapy." (PMID 28158206, 2017). "In addition, activation of MET has been observed in response to treatment with EGFR TKIs in lung cancers and anti-EGFR antibodies in colorectal cancers." (PMID 28418880, 2017). "EGFR has become an important biological target for lung cancer." (PMID 28615068, 2017). "We found that T0901317 could make natural EGFR‐TKI‐resistant A549 human lung cancer cells sensitive to EGFR‐TKI treatment and that this was dependent on LXRβ expression." (PMID 28097086, 2017). "Detecting EGFR amplification and protein in matching wild-type and activated status may contribute towards better mechanics exploration for lung cancer development in Yunnan." (PMID 28107191, 2017). "Compensatory activation of SRC occurs in lung cancer cells with acquired resistance to EGFR-TKIs." (PMID 29050315, 2017). "This makes EGFR an important target for lung cancer therapy." (PMID 28158983, 2017). "We also tested the possibility of forming an EGFR-YES-YAP1 complex in lung cancer cells." (PMID 29163769, 2017). "Since cell proliferation was affected in most EGFR mutated cells following FAM83H-AS1 knockdown, we selected the two most affected lung cancer cells, PC-9 (TKI sensitive) and H1650 (TKI resistant), for cell invasion and migration studies using Boyden chamber matrix assays." (PMID 28198463, 2017). "For the first time, we demonstrate that EGFR mutations are prognostic in NSCLC patients without family history of lung cancer in first-degree relatives but not in patients with a positive family history in this study." (PMID 28486527, 2017). "We also focus on anti-lung cancer drug development and EGFR-related drug resistance." (PMID 28430586, 2017). "Moreover, our patients had an equal chance for treatment owing to the fact that patients are reimbursed by the Taiwan National Health Insurance Administration for novel lung cancer therapies, such as EGFR-TKIs and pemetrexed, received over the study period." (PMID 29228697, 2017).
lung cancer (continued). "Indeed, in one study, exogenous HGF induced resistance to an anti-EGFR antibody in lung cancer cells (via the Met/Gab1/Akt signaling pathway)." (PMID 28619066, 2017). "The T790M mutation in EGFR has also been reported to disproportionately affect risk of lung cancer in never-smokers as opposed to heavy smokers, with the nonsmoking group having approximately a 31% risk increase." (PMID 28106732, 2017). "In addition, we have shown that activation of NF-κB rescues EGFR-mutant lung cancer cells from EGFR-TKI treatment." (PMID 28871105, 2017). "In conclusion, the emerging role of miRNAs as regulators could not only active EGFR signaling, but also the lung cancer cells resistance to anti-EGFR therapy." (PMID 28430586, 2017). "E7050, a dual inhibitor of Met and vascular endothelial growth factor receptor two kinase, and EGFR-TKIs suppressed tumor progression in erlotinib-resistant cancer cell lines and in HGF-induced EGFR-TKI-resistant lung cancer cell lines that also have a mutation in EGFR." (PMID 28619066, 2017). "In lung cancer patients, sortilin expression decreased with increased pathologic grade, and expression of sortilin was strongly correlated with survival, especially in patients with high EGFR expression." (PMID 29084952, 2017). "Alternatively, the differential rate of acquiring or eliminating EGFR, ALK, or ROS1 lung cancer somatic mutations may be also influenced by the inheritance of the EGLN1D4E/C127S variant which modulates HIFs-stability." (PMID 28036300, 2017). "In order to understand the correlation between miR-1 and EGFR signaling activity in clinical lung cancer specimens, we utilized the lung adenocarcinoma cancer data set containing both mRNA and miRNA data from TCGA and performed a gene set enrichment analysis (GSEA)." (PMID 28537886, 2017). "In addition, hyperactivation of HER3 has also been reported to negatively correlate with the response of lung cancer cells to anti-EGFR therapy." (PMID 28881753, 2017). "For instance, third-generation EGFR TKIs are being developed as part of a strategy to overcome treatment resistance to first- and second-generation EGFR TKIs in lung cancer patients; however, resistance to third-generation EGFT TKIs such as AZD9291 and HM61713 are also being arise." (PMID 29143801, 2017). "Epidemiological studies of lung cancer showed that EGFR mutations occur more frequently in never smoker East Asia, while KRAS mutations occur more frequently in smokers and less common in never smoker East Asia." (PMID 28430611, 2017). "Meanwhile activations of other signaling pathways, such as ERBB2 and PIK3CA may mediate resistance of lung cancers to EGFR-targeting therapies." (PMID 28591695, 2017). "Importantly, co-targeting EGFR (in lung cancer) or ALK (in NB) and the molecules that drive these pathways can reverse TKIs resistance." (PMID 29143801, 2017). "DUSP4, which belongs to dual-specificity phosphatase (DUSPs) family, regulating the activity and location of MAPKs, is a negative regulator of extracellular-regulated kinase activity and is upregulated in EGFR-mutant lung cancer cell lines compared with K-ras-mutant cells." (PMID 28500316, 2017). "For instance, somatic mutations in EGFR and translocation of ALK (both genes known to affect lung cancers) occur at higher rates in nonsmoking lung cancer patients than in the tumors of smoking lung cancer patients." (PMID 28106732, 2017). "In summary, our data suggest a negative association between the levels of EGFR and miR-370 expression in human lung cancer cell lines and non-tumor bronchial epithelial cells." (PMID 29152147, 2017). "Lung cancer of never smokers exhibited significantly higher ctDNA mutation rates as well as higher EGFR and ERBB2 mutations than ever smokers." (PMID 28472989, 2017).
lung cancer (continued). "However, the appearance of tumors resistant to EGFR T790M-targeted drugs such as osimertinib, WZ4002, and rociletinib has continuously caused serious problems for treating patients with lung cancer." (PMID 29050315, 2017). "Our results indicate that lung cancer cell lines with EGFR mutations (parental cells) do not harbor high PD-L1 protein expression." (PMID 29119113, 2017). "The effect of bevacizumab plus EGFR-TKI was also demonstrated in the Okayama Lung Cancer Study Group Trial 1001, which suggested that bevacizumab plus gefitinib could achieve 14.4 months PFS." (PMID 28977977, 2017). "For example, a subset of lung cancer patients which do not bear activating EGFR mutations can achieve clinical responses to EGFR inhibitors, or also a good proportion of BRAF mutated melanoma patients do not respond to BRAF inhibitors." (PMID 28903768, 2017). "In this study, we aimed to identify new drug candidates for treating EGFR TKI-resistant lung cancer cells by employing the popular and efficient strategy of drug repurposing, given that new drug development and approval is often protracted and drug attrition rate is notoriously high." (PMID 29238696, 2017). "Therefore, further investigation in a large cohort is warranted to validate the distinct prevalence of mutations in EGFR and LRP1B among LUAD patients with COPD and clarify the impact of COPD on the survival of the patients with lung cancer." (PMID 28522810, 2017). "In lung cancer, transcriptional induction of ERBB3 causes intrinsic resistance to MEK inhibition in KRAS-mutant cancers, and acquired resistance to EGFR inhibitors was found to result from amplification of MET." (PMID 28145866, 2017). "In this study, we investigated if liver X receptor (LXR) agonist T0901317 could reverse the resistance of lung cancer cell lines A549 and H1650 to EGFR‐TKI treatment." (PMID 28097086, 2017). "As for the effect of family history of lung cancer on survival of the patients, it has been examined in two different cohorts where the prognostic impact was contrasted, and EGFR activating mutations were not considered." (PMID 28486527, 2017). "Epidermal growth factor receptor (EGFR) is a plausible target; however, EGFR mutations are primarily found in lung cancer in never-smokers." (PMID 27708216, 2016). "We proposed that higher angiogenic ability observed in lung cancer cells with exon 19 deletion was through increased phosphorylation of EGFR and downstream pathways, thus the growth of lung tumors with exon 19 deletion may rely more on angiogenesis." (PMID 27362942, 2016). "EGFR is known to play a central role in stemness, particularly in colon and lung cancer stem cells." (PMID 27374096, 2016). "However, EGFR was reported to related with PD-related genes such as PARK2, whose mutation was proved to be associated with lung cancer." (PMID 27801674, 2016). "Moreover, we demonstrated that miR-218-5p plays a critical role in suppressing the proliferation and migration of lung cancer cells probably by binding to EGFR." (PMID 27057632, 2016). "Notably, inhibition of GPR171 synergistically enhanced the tumoricidal activity of an epidermal growth factor receptor (EGFR) inhibitor in lung cancer cells." (PMID 26760963, 2016). "Our data provide rationale and a model for addressing early TKI responses in lung cancer, as well as raises the paradigm of how immediate-early tumor responses to EGFR-TKIs in “pre-clinical” in vivo models predicts long term therapy response in human lung adenocarcinoma." (PMID 27494838, 2016). "Epidermal growth factor receptor (EGFR) induced activation of the transcription factor NF-κB may be involved in the malignant behavior of EGFR overexpressing tumor cells, such as in lung cancer and gastric carcinoma." (PMID 27250029, 2016).
lung cancer (continued). "In contrast to the situation in lung cancer, Cx43 was increased with the formation of cell-cell communication in the resistant tumor cells and this increase was induced by epidermal growth factor receptor (EGFR) activated JNK-ERK1/2-AP-1 signaling." (PMID 27229305, 2016). "Patients diagnosed with lung cancer harboring these EGFR double mutation do not respond to EGFR-TKI." (PMID 27869781, 2016). "Twenty-one patients with EGFR-mutant lung cancer who were naïve to EGFR-TKI were enrolled." (PMID 27708242, 2016). "In addition, AKT activation by EGFR is correlated with membrane PD-L1 expression and poor survival in lung cancer patients." (PMID 27572267, 2016). "In the past decades, several membrane-located proteins were discovered that could successfully be targeted, i.e. estrogen/progesterone receptor (ER/PR) in breast cancer patients and epidermal growth factor receptor (EGFR) in lung cancer patients." (PMID 26943581, 2016). "IL10 and EGFR co-regulation produces a vicious cycle for lung cancer development." (PMID 26956044, 2016). "Despite the development of novel chemotherapeutic agents and regimens for lung cancer treatment, acquired and inborn drug resistance, including epidermal growth factor receptor tyrosine kinase inhibitor (EGFR-TKI) resistance, have been major barriers for chemotherapy." (PMID 27558531, 2016). "How might our observations be used to inform the use of vitamin D metabolites for management of EGFR mutant lung cancers?" (PMID 26654942, 2016). "Patients with EGFR-mutated lung cancers have a better prognosis compared with patients without mutations, regardless of therapy type." (PMID 27655296, 2016). "The implication of our findings is that dietary vitamin D3 supplementation may be used as a safe and effective approach to increase 25D3 levels and slow the growth of EGFR mutant lung cancer, even in tumors that express CYP27B1 at low levels." (PMID 26654942, 2016). "EGFR signaling pathways in lung cancer have been reported to promote angiogenesis, cellular proliferation and epithelial-mesenchymal transition (EMT); and all of which may mediate oncogenic progression and metastasis." (PMID 27486770, 2016). "Considering the nearly unavoidable resistance to EGFR-TKIs, we propose that a resistance mechanism may also exist in wild-type EGFR lung cancer." (PMID 26919104, 2016). "We next measured TOPK levels in lung cancer cell lines with varied sensitivity to EGFR-TKIs." (PMID 26745678, 2016). "The EGFR pathway represents the pioneer of personalised medicine in lung cancer." (PMID 27433281, 2016). "In this study, we established an in vivo imaging model for LMC with EGFR mutant lung cancer cell lines harboring an exon 19 deletion in EGFR and evaluated the effect of first generation EGFR-TKIs, erlotinib, second generation afatinib, and third generation AZD9291." (PMID 26716903, 2016). "The tumor tissue showed 110-kDa sEGFR isoforms with isoelectric point (pI) >6, while plasma samples showed 110-kDa sEGFR isoforms with an extremely acidic pH (3.87–4.74), indicating that the secreted EGFR isoforms in plasma and in lung cancer were molecularly heterogeneous." (PMID 27104520, 2016). "Since epidermal growth factor receptor (EGFR) is commonly deregulated in pre-malignant lung epithelium, targeting EGFR may arrest the development of lung cancer." (PMID 27458163, 2016). "Intratumoural EGFR homogeneity in lung cancers has long been assumed." (PMID 27046167, 2016). "A phase I study of vorinostat 1 and VEGFR inhibitor gefitinib 30 in combination therapy has been approved for targeting resistance by B cell chronic lymphocytic leukemia-lymphoma-like 11 gene (BIM) polymorphysim in EGFR mutant lung cancer (VICTORY-J) (NCT02151721)." (PMID 27752293, 2016). "Among the retrospective familial lung cancer cohort (n = 88), 11 patients (12.5%) were excluded while analyzing the overall EGFR mutation frequency and spectrum due to non-adenocarcinoma histology." (PMID 27449093, 2016).
lung cancer (continued). "A recent study demonstrated that PA-MSHA could directly induce G0-G1 cell cycle arrest of the cancer cells, suggesting the combination of PA-MSHA and gefitinib inhibits lung cancer cell proliferation through an EGFR independent pathway." (PMID 27283902, 2016). "Well-characterized examples include the BCR-ABL translocation in Philadelphia chromosome-positive leukemias, which confers sensitivity to the ABL tyrosine kinase inhibitor imatinib, as well as epidermal growth factor receptor (EGFR)-mutant lung cancers, which are sensitive to EGFR inhibition." (PMID 27855189, 2016). "These guidelines exclude wt-EGFR lung cancer patients for TKI administration." (PMID 26646697, 2016). "Lastly, we investigated the correlation of PD-L1 expression to sensitivity to EGFR inhibitors and expression of various genes critical for antigen presenting pathways using drug sensitivity and gene expression dataset of 186 lung cancer cell lines from Cancer Cell Line Encyclopedia." (PMID 27467256, 2016). "We hypothesize here that inhibition of OxPhos suppresses the development of osimertinib resistance in EGFR-mutant lung cancer cell lines." (PMID 27861144, 2016). "Therefore, we assessed a series of lung cancer cell lines with wide range of known sensitivity to erlotinib for the impact of EGFR inhibitors on MHC-I, MHC-II, and PD-L1 expression in the presence or absence of inflammatory cytokine, IFNγ." (PMID 27467256, 2016). "For example, the molecular status of the epidermal growth factor receptor (EGFR) in lung cancer has been shown to have influence on the prognosis of patients and may indicate the introduction of alternative therapies." (PMID 27437769, 2016). "Addition of the LL-37 peptide at low concentrations (5 ng/ml) to lung cancer cell lines induced phosphorylation of the EGFR and activation of downstream MAP kinase signaling pathways, leading to enhanced proliferation and growth of anchorage-independent colonies." (PMID 26395996, 2016). "Only the lung cancer effusion with the sensitive EGFR mutation, but not the EGFR wild-type one, responded to erlotinib in a dose-dependent manner, which confirms the relevance of this new in vitro test system." (PMID 27548442, 2016). "In NHANES III participants, higher serum 25D3 concentrations were associated with decreased risk of dying from lung cancer only among nonsmokers (where EGFR gene mutations are more common)." (PMID 26654942, 2016). "In addition, it significantly inhibited the IFNγ induced overexpression of PD-L1 proteins especially in EGFR driven lung cancer cell lines (p<0.05)." (PMID 27467256, 2016). "In summary, we have found that tumor suppressor MIIP promotes EGFR degradation via both the proteasomal and lysosomal pathways, resulting in downregulation of EGFR downstream signaling and ultimately in inhibition of lung cancer cell growth." (PMID 26824318, 2016). "EGFR downstream signaling seems to be targeted by Carbon Ion in Lung Cancer, as in our study." (PMID 27374096, 2016). "Previous reports showing soluble EGFR protein in serum of patients with metastatic breast and lung cancer could support our results." (PMID 27152724, 2016). "However, the allosteric inhibitor EAI045 in combination with cetuximab exhibited mechanistic synergy and was effective in mouse models of lung cancer driven by EGFR L858R/T790M and by EGFR L858R/T790M/C797S." (PMID 28149837, 2016). "However, even in lung cancer cells with wild-type EGFR, EGFR phosphorylation was inhibited by gefitinib, accompanied by modestly suppression of cell proliferation." (PMID 26919104, 2016). "Therefore, our results suggests that EGFR-positive lung cancers exhibit more GGO components, less lymph node invasion, and a higher tendency to metastasize to other organs, compared to the KRAS- and ALK-positive subtypes." (PMID 27518729, 2016). "However, PIK3CA mutations have been identified in a small percentage of EGFR-mutant lung cancers acquiring resistance to EGFR-TKIs." (PMID 27455248, 2016).